TWIST2 (twist family bHLH transcription factor 2)
Diseases named in the same sentence as TWIST2 in open-access papers (continued):
Sharing a sentence is not in itself a finding about the gene and the disease.
ovarian carcinoma (7 papers, 2013 to 2022). A malignant neoplasm originating from the surface ovarian epithelium. "They found that TWIST2 expression was up-regulated in resistant variant C13K ovarian cancer cell line compared to the cisplatin sensitive ovarian cancer cell line OV200876." (PMID 35523936, 2022). "It showed that DNA methylation changes of CDH1, EPCAM and TWIST2 genes underlie the EMT induction in cisplatin resistant ovarian cancer cell line." (PMID 35523936, 2022). "Here, we investigate the role of Twist2 in ovarian cancer invasion and metastasis as well as the underlying molecular mechanisms." (PMID 24244294, 2013). "In this study, we provide the first evidence that Twist2 expression is associated with high FIGO stage in ovarian cancer." (PMID 24244294, 2013). "Here, we investigate the role of Twist2 in ovarian cancer progression and the potential molecular mechanisms underlying the Twist2-induced cancer invasion and metastasis." (PMID 24244294, 2013). "The aim of the present study was to investigate the Twist2 expression pattern in a cisplatin-sensitive ovarian cancer cell line and the resistant variant (C13K), and to determine the effect Twist2 has on the regulation of cell growth and cisplatin-induced apoptosis in ovarian cancer cells." (PMID 24944676, 2014). "Thus, the present study investigated Twist2 expression patterns in ovarian cancer, the role in chemoresistance and also a possible underlying mechanism." (PMID 24944676, 2014). "The upregulation of Twist2 is associated with HIF-1α expression in ovarian cancer." (PMID 23946798, 2013). "Twist2 increased in epithelial ovarian cancers associated with HIF-1α expression." (PMID 23946798, 2013). "Clinical pathological characteristics of Twist2-associated ovary cancer." (PMID 24244294, 2013). "The effects of apoptosis were examined in Twist2 silenced ovarian cancer cells using Annexin-V and PI double-staining and measured by flow cytometry." (PMID 24944676, 2014). "The results of the current study provide support for this potential novel gene therapy with Twist2 for the treatment of chemoresistant human ovarian cancer." (PMID 24944676, 2014). "In conclusion, the present study demonstrates that Twist2 plays a crucial role in the chemoresistance of ovarian cancer." (PMID 24944676, 2014). "In colorectal and ovarian cancers, miR-138 suppressed cancer cell migration and metastasis through interfered with TWIST2, SOX4 and HIF1-a." (PMID 24941171, 2014). "Downregulation of Twist2 expression facilitated apoptosis and recovered the sensitivity of chemoresistant ovarian cancer through the AKT/GSK-3β pathway." (PMID 24944676, 2014). "The results of the present study indicated that Twist2 plays a crucial role in the chemoresistance of ovarian cancer." (PMID 24944676, 2014). "Our data indicates that upregulation of Twist2 is correlated with the FIGO stage in human ovarian cancers." (PMID 24244294, 2013). "Twist2 expression was significantly increased in ovarian cancer (70.24%, 59 in 84 cases) relative to normal ovarian tissue (P<0.05)." (PMID 24244294, 2013). "Overall, out of the 30 cases of ovarian tissue (including the primary ovarian cancer and normal ovarian tissues), 16 cases (53%) showed Twist2 positive expression and 18 cases (60%) showed HIF-1α-positive expression." (PMID 23946798, 2013). "Our data suggest that upregulation of Twist2 is correlated with the FIGO stage in human ovarian cancers." (PMID 24244294, 2013). "In the present study, Twist2 was demonstrated to protect ovarian cancer cells from apoptosis under hypoxic conditions, as well as enhance cell survival in this unfavorable microenvironment." (PMID 23946798, 2013). "The acquired expression of Twist2 was able to promote the survival of ovarian cancer cells through Akt phosphorylation under DFO-induced hypoxic stress." (PMID 23946798, 2013).
ovarian carcinoma (continued). "Twist2 expression was detected by Immunohistochemistry (IHC) on tissue microarray of human ovarian cancers with scoring procedure according to the staining intensity and pattern." (PMID 24244294, 2013). "When Twist2 over-expresses in the ovarian cancer cells, the cancer cells morphology was transformed into fibroblast-like shape along with increased motility and invasiveness, while no change was found in cell proliferation." (PMID 24244294, 2013). "In conclusion, it was demonstrated that Twist2 was expressed at significantly higher levels in ovarian carcinoma cells and in correlation with HIF-1α." (PMID 23946798, 2013). "Collectively, these data indicated that β-catenin is involved in Twist2-induced EMT in ovarian cancer." (PMID 24244294, 2013). "To the best of our knowledge, we show for the first time that Wnt activation in Twist2-induced EMT progress in ovarian cancer, providing new insights into their metastasis." (PMID 24244294, 2013). "In this report, we demonstrated that nuclear β-catenin is accumulated in Twist2-induced EMT cells to facilitates ovarian cancer invasion and metastasis." (PMID 24244294, 2013). "Twist2 gene was stably introduced into SKOV-3 ovarian cancer cells to examine the changes of cellular morphology, motility, invasiveness, and EMT molecular markers." (PMID 24244294, 2013). "Based on the correlation between the two molecules, we propose that Twist2 is involved in ovarian cancer hypoxia." (PMID 23946798, 2013). "A series of matched tissue sections from formalin-fixed and paraffin-embedded human primary ovarian cancer and normal ovarian tissues were examined via immunohistochemical analysis to assess the correlation between Twist2 and HIF-1α expression." (PMID 23946798, 2013). "Twist2 promoted ovarian cancer cell survival when treated with DFO, particularly when combined with serum starvation." (PMID 23946798, 2013). "In the present study, a pair of chemosensitive and chemoresistant (C13K) ovarian cancer cell lines were used to investigate the possible roles of Twist2 in the regulation of cisplatin-mediated apoptosis and cisplatin resistance in human ovarian epithelial cancer." (PMID 24944676, 2014). "The role of Twist2 in the growth of ovarian cancer cells was determined by an MTS assay." (PMID 24944676, 2014). "Thus, the present study investigated the correlation between the AKT/GSK-3β pathway and Twist2 expression in ovarian cancer." (PMID 24944676, 2014). "Therefore, the results indicate that combination chemotherapy targeting Twist2 expression is likely to improve the treatment of ovarian cancer." (PMID 24944676, 2014). "The present study investigated whether the exogenous overexpression of Twist2 promotes ovarian cancer cell survival under hypoxia." (PMID 23946798, 2013). "Twist2-overexpressing stable ovarian cancer cell lines were then constructed." (PMID 23946798, 2013). "We showed Twist2 is highly expressed in ovarian cancer tissues." (PMID 24244294, 2013). "The Twist2 expression in ovarian cancer patients was elevated compared with the control." (PMID 23946798, 2013). "Ectopic expression of Twist2 in ovarian cancer cells confers an EMT phenotype." (PMID 24244294, 2013). "The human ovarian cancer cell line HO-8910 was selected to further assess whether the stable overexpression of Twist2 in human ovarian cancer cells was able to alter cell survival in vitro." (PMID 23946798, 2013). "Twist2 expression is significantly increased in ovarian cancers along with the FIGO disease stage, indicating that Twist2 may be associated with ovarian cancer metastasis." (PMID 24244294, 2013). "To verify whether Twist2 is a crucial mediator of ovarian cancer, progression, we established cell lines stably overexpressing Twist2." (PMID 24244294, 2013). "We hypothesized that Twist2 assists in the survival of ovarian cancer cells leading to a more aggressive phenotype under hypoxic conditions." (PMID 23946798, 2013).
ovarian carcinoma (continued). "Overexpression of Twist2 induced the EMT phenotypes in human ovarian cancer cells in vitro." (PMID 24244294, 2013). "The present study evaluated the expression of HIF-1α and Twist2 and further investigated whether Twist2 is involved in hypoxia-induced apoptosis in ovarian cancer." (PMID 23946798, 2013). "In addition, the inhibition of the PI3-K/Akt pathway partly attenuated the Twist2-mediated Akt phosphorylation in the ovarian cancer cells." (PMID 23946798, 2013). "We further hypothesized that Twist2 assists in the survival of ovarian cancer cells under hypoxic conditions, as well as in inducing EMT." (PMID 23946798, 2013). "Therefore, the expression of Twist2 was examined in the present study and observed to be upregulated in ovarian cancer." (PMID 23946798, 2013). "Also in ovarian cancer TWIST2 expression is correlated with disease stage." (PMID 25528769, 2015). "However, whether Twist2 suppression increases the chemosensitivity of ovarian cancer cells to chemotherapeutic agents remains unclear." (PMID 24944676, 2014). "However, the role that Twist2 plays in drug resistance and the possible underlying mechanism in ovarian cancer has not yet been established." (PMID 24944676, 2014). "Thus, in the present study, the AKT/GSK-3β pathway was investigated to determine whether it played a role in Twist2-mediated cisplatin-resistance in ovarian cancer." (PMID 24944676, 2014). "In addition, the downregulation of Twist2 expression may facilitate apoptosis and recover the sensitivity of chemoresistant ovarian cancer through the protein kinase B/glycogen synthase kinase-3β pathway." (PMID 24944676, 2014). "To further determine whether expression of Twist2 indeed promotes EMT in these ovarian cancer cells, we examined the expression of E-cadherin and N-cadherin, two well-established epithelial to mesenchymal makers, in Twist2-expressing and the vector-transfected SKOV-3 cells." (PMID 24244294, 2013). "Overexpression of Twist2 induced the EMT phenotype including downregulation of E-cadherin, and upregulation of N-cadherin and β-catenin in human ovarian cancer cells, suggesting that Twist2 might promote β-catenin release from the E-cadherin/β-catenin complex through inhibition of E-cadherin." (PMID 24244294, 2013). "However, Twist2 remains to be investigated under hypoxia in ovarian cancer." (PMID 23946798, 2013). "Results show ERα occupancy in HOXB3, TGM1, TWIST2, and WT1 gene promoters, which are all relevant for ovarian cancer, and DOT1L co-binding with ERα only in the TWIST2 and WT1 promoter regions." (PMID 31689915, 2019). "Therefore, Twist2 depletion may be a promising approach to ovarian cancer therapy." (PMID 24944676, 2014). "Moreover, Twist2 may be involved in the HIF-1α signaling pathway in ovarian cancer." (PMID 23946798, 2013). "However, whether Twist2 promotes human ovarian cancer progression remains to be elucidated." (PMID 24244294, 2013). "However, whether Twist2 promotes human ovarian cancer progression remains poorly understood." (PMID 24244294, 2013). "Interesting, the Twist2/SKOV-3 cells increased the migration and invasion of ovarian cancer cells, as assessed by scratch-wound assay and invasion assay." (PMID 24244294, 2013). "Twist2 is an EMT regulator, however, it remains poorly understood in ovarian carcinoma." (PMID 23946798, 2013).
lung carcinoma (6 papers, 2021 to 2025). "In lung cancer, TWIST2 induces oxidative stress in cancer cells by regulating the FGF21-mediated AMPK/mTOR signaling pathway and prevents lung cancer from progressing." (PMID 36428665, 2022). "However, additional transcription factors may be involved including HMGA2, ZEB1 and TWIST2, known to be involved in lung cancer." (PMID 41184222, 2025).
colorectal cancer (5 papers, 2013 to 2022). A primary or metastatic malignant neoplasm that affects the colon or rectum. "TWIST2 methylation changes were observed in various cancers such as colorectal cancers, prostate cancer, and chronic lymphocytic leukemia, this epigenetic event might be the underlying mechanism for TWIST2 transcriptional regulating." (PMID 35523936, 2022). "We evaluated TWIST1 and TWIST2 methylation status in six well-established colorectal cancer cell lines and their corresponding immunohistochemistry detection." (PMID 25528769, 2015). "In colorectal cancers, recent results from Yu and colleagues suggest that expression of TWIST2 is a valuable adverse prognostic marker." (PMID 25528769, 2015). "The results of this study suggest that TWIST1 and to a lesser degree TWIST2 expressed within the tumor stroma could contribute to the EMT-like tumor budding phenotype in colorectal cancers." (PMID 25528769, 2015). "Other groups have reported on TWIST1 and TWIST2 methylation in colorectal cancer." (PMID 25528769, 2015). "Strikingly less is known about TWIST2, particularly in colorectal cancer." (PMID 25528769, 2015). "Tumor budding in colorectal cancer is likened to an epithelial-mesenchymal transition (EMT) characterized predominantly by loss of E-cadherin and up-regulation of E-cadherin repressors like TWIST1 and TWIST2." (PMID 25528769, 2015). "In colorectal cancers, TWIST1 and TWIST2 expression was essentially restricted to stromal cells." (PMID 25528769, 2015).
gastric cancer (5 papers, 2015 to 2025). A primary or metastatic malignant neoplasm involving the stomach. "In gastric cancer cells, EMP3 can act as a downstream effector of TWIST1 and TWIST2 and participate in the EMT of gastric cancer." (PMID 36217151, 2022). "In the present study, it was observed that IGF-I induced EMT and upregulated ZEB2, but not ZEB1, Twist1 or Twist2, in gastric cancer BGC-823 cells." (PMID 25435948, 2015).
glioma (5 papers, 2021 to 2024). A benign or malignant brain and spinal cord tumor that arises from glial cells (astrocytes, oligodendrocytes, ependymal cells). "Taken together, our findings suggest that ACOT12 can serve as a tumor suppressor by regulating TWIST2 and mesenchymal transition in glioma." (PMID 35986010, 2022). "MiR-155-5p overexpression results in the upregulation of EMT markers, including TWIST2, vimentin and N-cadherin, suggesting that miR-155-5p promotes mesenchymal transition in glioma cells." (PMID 35986010, 2022). "The results showed that the expression of TWIST2 and EMT markers was significantly increased after knockdown of ACOT12 with siRNA, which indicated that depletion of ACOT12 was able to enhance mesenchymal transition in glioma cells." (PMID 35986010, 2022). "To explore whether the relationship between ACOT12 and EMT is also involved in the progression of glioma, we validated the effect of modulating ACOT12 expression on the expression levels of TWIST2 and other EMT markers, including vimentin and N-cadherin, by RT-qPCR and western blotting." (PMID 35986010, 2022). "The results showed that the mRNA expression levels of Twist1, Twist2, Zeb1, Zeb2 and Slug2 maintained significantly negative correlations with the mRNA expression levels of Presenilin1 in gliomas of all WHO grades, but the relationships were not significant between Presenilin1 and Slug1." (PMID 34781973, 2021). "Moreover, most EMT biomarkers, including N-cadherin, snail, slug, vimentin, TWIST1, and TWIST2, were significantly correlated with BDKRB2, which suggested that BDKRB2 might profoundly interact with these key molecules of EMT, further confirming the involvement of BDKRB2 in glioma EMT." (PMID 33686021, 2021).
osteosarcoma (5 papers, 2015 to 2024). A usually aggressive malignant bone-forming mesenchymal neoplasm, predominantly affecting adolescents and young adults. "TWIST2 may function as a tumor suppressor and has been shown to inhibit formation of a microenvironment conducive to tumor growth in a murine osteosarcoma model." (PMID 25528769, 2015). "Moreover, TWIST2 was reported to inhibit tumor formation in a mouse osteosarcoma model." (PMID 29156759, 2017).
pancreatic cancer (4 papers, 2016 to 2023). "In this study, we investigated HIF-2α expression and VM by immunohistochemistry in 70 pancreatic cancer patients as well as the role of Twist1and Twist2 in HIF-2α-induced VM in vitro and in vivo." (PMID 28599281, 2017). "The results showed that Twist1 and Twist2 expressions were located in the cytoplasm of pancreatic cancer cells." (PMID 26842802, 2016). "In the present study, we found that Twist1, Twist2 and E-cadherin were regulated by HIF-2α in pancreatic cancer cells." (PMID 26842802, 2016). "Clinical tissues IHC staining showed that Twist2 and E-cadherin expression had an obviously negative correlation in pancreatic cancer." (PMID 26842802, 2016). "Clinical tissues IHC staining showed that Twist2 and E-cadherin expression had an obviously negative correlation in pancreatic cancer tissues, however, it had no obvious correlation between Twist1 and E-cadherin." (PMID 26842802, 2016).
acute lymphoblastic leukemia (3 papers, 2017 to 2018). Leukemia with an acute onset, characterized by the presence of lymphoblasts in the bone marrow and the peripheral blood. "In hematological malignancies, several studies have reported on the role of the EMT transcription factors TWIST1 and TWIST2 in both myeloid and lymphoblastic leukemia." (PMID 29925392, 2018). "In acute lymphoblastic leukemia, overexpression of TWIST2 inhibits cell growth, prompts apoptosis and increases sensitivity to chemotherapeutic agents." (PMID 29156759, 2017).
colon cancer (3 papers, 2017 to 2021). "In this study by using publicly available microarray datasets, we for the first time showed a negative correlation between EVI1 and all the known EMT related transcription factors (SNAIL, SLUG, ZEB1, ZEB2, TWIST1, and TWIST2) in colon cancer patient samples." (PMID 29339729, 2018).
Obesity (3 papers, 2019 to 2021). Accumulation of substantial excess body fat. "Low expression of TWIST2 is involved in obesity, but this gene may link with insulin resistance." (PMID 30678306, 2019).
prostate carcinoma (3 papers, 2013 to 2022). A carcinoma that arises from epithelial cells of the prostate gland. "Overexpression of the EMT-promoting factors SNAIL1, TWIST1 and TWIST2 reduced the ability of the prostate cancer cell line PC3 to form spheroids." (PMID 24124614, 2013). "The Twist box is required for prostate cancer cells to colonize metastatic lung lesions and extrathoracic metastases, while the glycine-rich domains, which are absent in Twist2, may be used to interact with proteins, resulting in differences in protein function between TWIST1 and TWIST2." (PMID 36140527, 2022).
breast tumor (2 papers, 2021 to 2022). "To further examine the role of ID4 in cancer stemness, we knocked down ID4 in MDA-MB-468 breast tumor cells using SMARTpool siRNAs, and tested the expression of a panel of stemness genes including Twist1, Twist2, Snail, Slug, BMP2, IRF1, SOX4, Foxk1 and Notch3." (PMID 36291790, 2022). "The METABRIC database (1904 human breast tumors) consistently revealed a positive association of NME4 with epithelial markers CDH1 and KRT18 and a negative association with mesenchymal markers CDH2 and VIM as well as many EMT drivers like ZEB1, ZEB2, SNAI2, TWIST1, and TWIST2." (PMID 34674701, 2021).
chronic lymphocytic leukemia (2 papers, 2013 to 2022). "Of note, the DNA hypermethylation in TSGs, such as DAPK1, ID4, SFRP1, TWIST2 and ZAP70, has been identified to play a role in the pathogenesis or prognosis of chronic lymphocytic leukemia (CLL)." (PMID 24373626, 2013).
craniosynostosis (2 papers, 2014 to 2018). Craniosynostosis is defined as the premature fusion of one or more cranial sutures leading to secondary distortion of skull shape resulting in skull deformities with a variable presentation. "Twist1 and Twist2 haploinsufficient mice did not present with premature ossification and craniosynostosis; instead they displayed reduced bone formation, impaired proliferation and differentiation of osteoprogenitors." (PMID 24971743, 2014).